LINC01320 (long independently transcribed non-coding RNA 1320)
Synonyms: LINC01317
Gene: Long non-coding RNA gene on chromosome 2 (33,706,806 to 34,738,231, forward strand). Ensembl gene ENSG00000228262.
Diseases named in the same sentence as LINC01320 in open-access papers:
LINC01320 is named in the same sentence as 5 diseases in open-access papers, as found by Europe PMC text mining. Sharing a sentence is not in itself a finding about the gene and the disease. The quoted sentences say what the papers report.
gastric cancer (3 papers, 2021 to 2023). A primary or metastatic malignant neoplasm involving the stomach. "The m6A-mediated upregulation of LINC01320 promotes the proliferation, migration, and invasion of gastric cancer via the miR495-5p/RAB19 axis." (PMID 35778697, 2022). "LINC01320 overexpression promoted the proliferation, migration, and invasion of gastric cancer cells, while LINC01320 knockdown exerted the opposite effects." (PMID 34288797, 2021). "Overexpressed LINC01320 contributed to the aggressive phenotype of gastric cancer cells via regulating the miR-495-5p/RAB19 axis." (PMID 34288797, 2021). "We found that LINC01320 can promote the proliferation, migration, and invasion of gastric cancer cells by sponging miR-495-5p." (PMID 34288797, 2021). "As LINC01320 is up-regulated in gastric cancer tissues and cell lines, we supposed that LINC01320 should play critical roles in the development of gastric cancer." (PMID 34288797, 2021). "Mechanistically, METTL14-mediated m6A modification induces the up-regulation of LINC01320, which subsequently affects gastric cancer progression through the miR-495-5p/RAB19 axis." (PMID 34288797, 2021). "Bioinformatics analysis revealed that LINC01320 was overexpressed in gastric cancer." (PMID 34288797, 2021). "LINC01320 was highly expressed in gastric cancer tissues and cells." (PMID 34288797, 2021). "Further, LINC01320 was significantly overexpressed in gastric cancer cells." (PMID 34288797, 2021). "Moreover, down-regulation of RAB19 antagonized the aggressive behaviors of gastric cancer induced by LINC01320 overexpression." (PMID 34288797, 2021). "Moreover, overexpression of LINC01320 promoted the proliferation, invasion, and migration of gastric cancer cells, while knockdown of LINC01320 exerted the opposite effects." (PMID 34288797, 2021). "In gastric cancer, METTL14-mediated m6A modification led to LINC01320 upregulation, which promoted an aggressive phenotype of increased cancer cell proliferation, migration, and invasion via regulating the miR-495-5p/RAB19 axis." (PMID 37029420, 2023). "However, the potential roles of LINC01320 in gastric cancer are unknown." (PMID 34288797, 2021).
endometrial carcinoma (1 paper, 2021). A malignant tumor arising from the epithelium that lines the cavity of the uterine body. "In previous studies, LINC01320 is only highly expressed in the lncRNA expression profile of endometrial carcinoma and the lncRNA expression profile of myocardial infarction." (PMID 34976325, 2021).
renal carcinoma (1 paper, 2024). A carcinoma arising from the epithelium of the renal parenchyma or the renal pelvis. "To investigate the effect of LINC02609, LINC01320 and LICN01116 in ccRCC, we down-regulated the expression of LINC02609, LINC01320 and LICN01116 in renal cancer cell lines (786-O and A498)." (PMID 38263248, 2024).
LINC01320 also shares sentences with these, for which no sentence is quoted: cancer (1 paper); myocardial infarction (1).